KRAS (KRas proto-oncogene, GTPase)
Diseases named in the same sentence as KRAS in open-access papers (continued):
Sharing a sentence is not in itself a finding about the gene and the disease.
hilar cholangiocarcinoma (1 paper, 2022). A cholangiocarcinoma that arises from the junction, or adjacent to the junction, of the right and left hepatic ducts. "KRAS mutation analysis should be included in the routine pathologic evaluation of resected hilar cholangiocarcinoma in order to better stratify prognosis." (PMID 36139531, 2022). "The aim of this study was to evaluate the rate of KRAS mutation in a single-center homogeneous population, resected for hilar cholangiocarcinoma and its impact on prognosis." (PMID 36139531, 2022). "This single-center study showed that KRAS mutation was an independent predictor of poor OS following radical resection for hilar cholangiocarcinoma." (PMID 36139531, 2022). "The reported frequency of KRAS mutations and their prognostic impact in patients resected for hilar cholangiocarcinoma are controversial." (PMID 36139531, 2022). "The aim of this study was to evaluate the rate of KRAS mutations in a single-center homogeneous population resected for hilar cholangiocarcinoma and the subsequent impact on prognosis." (PMID 36139531, 2022). "The aim of this study was to evaluate the rate of KRAS mutations in a single-center homogeneous population resected for hilar cholangiocarcinoma and the impact on prognosis." (PMID 36139531, 2022). "Our study evaluated the KRAS mutation frequency in a homogeneous single-center population resected for hilar cholangiocarcinoma." (PMID 36139531, 2022). "The significance of this study was to evaluate if KRAS mutation analysis may have a role in the routine pathologic evaluation of resected hilar cholangiocarcinoma in order to better stratify prognosis." (PMID 36139531, 2022). "These two subtypes of tumors are both included in the term perihilar cholangiocarcinoma, but they may show different frequencies in KRAS mutation." (PMID 36139531, 2022). "KRAS mutation status was evaluated in 54 patients undergoing major hepatectomy combined with resection of the main biliary confluence and regional lymphadenectomy for hilar cholangiocarcinoma between 2001 and 2019." (PMID 36139531, 2022). "Indeed, KRAS mutation rate may be significantly higher in patients with hilar cholangiocarcinoma than that in patients with intrahepatic liver mass invading the hepatic hilum." (PMID 36139531, 2022). "Moreover, the study analyzed the frequency of KRAS mutation and its impact on OS in patients resected for a specific subtype of PHC: the hilar cholangiocarcinoma." (PMID 36139531, 2022). "The results of our study suggested that KRAS mutation in hilar cholangiocarcinoma was not rarely observed." (PMID 36139531, 2022). "Our study showed that KRAS mutation in hilar cholangiocarcinoma was not rarely observed." (PMID 36139531, 2022).
Hodgkins lymphoma (1 paper, 2018). A heterogeneous group of malignant lymphoid neoplasms of B-cell origin characterized histologically by the presence of Hodgkin and Reed-Sternberg (HRS) cells in the vast majority of cases.
Hypercalcemia (1 paper, 2014). An abnormally increased calcium concentration in the blood. "Also, there was a correlation between high KRAS expression and PTHrP-induced hypercalcemia." (PMID 28326248, 2014).
hypertensive nephropathy (1 paper, 2024). Kidney damage that results from chronically elevated blood pressure; complications include glomerular damage resulting in proteinuria and hematuria. "Collectively, in the hypertensive nephropathy samples and AngII-induced podocyte models, the renal injury markers were increased, autophagic flux was decreased, and differential miRNAs (miR-98-5p and miR-669b-5p), hub target genes (KRAS and NRAS), and transcription factor (RUNX2) were dysregulated." (PMID 39199205, 2024). "The expression of KRAS, MAPK1, NRAS, and PTEN was significantly upregulated in the tubulointerstitial region of patients with hypertensive nephropathy compared with healthy living donors." (PMID 39199205, 2024).
Hypomagnesemia (1 paper, 2018). An abnormally decreased magnesium concentration in the blood. "There were five trials of 1723 wild-type KRAS mCRC patients who received either cetuximab- or panitumumab-based chemotherapy, including 568 patients (33.0%) with clinical hypomagnesemia and 1155 patients (67.0%) with normal serum magnesium levels." (PMID 29391418, 2018).
hypophosphatemic rickets (1 paper, 2025). Rickets due to low serum phosphate concentrations, the cause of which can be nutritional or genetic. "At the same time, patients with HRAS mutations were more frequent to develop skeletal bone abnormalities, including hypophosphatemic rickets, than patients with KRAS mutations (65 vs. 27%, OR = 5.0, 95%CI = 1.4– 18.1, p = 0.015)." (PMID 41438146, 2025).
IgA nephropathy (1 paper, 2025). "The occurrence of external conditions conducive to tumorigenesis, such as IgA nephropathy, displayed a simultaneous involvement of other oncogenes such as KRAS, which contributed towards the upregulation of several other host genes, as indicated by common pathways." (PMID 39857756, 2025).
Inguinal hernia (1 paper, 2020). Protrusion of the contents of the abdominal cavity through the inguinal canal. "We discovered that PIK3R1, PTPN11, TGFBR1, CDC42, SOS1, and KRAS were the most essential inguinal hernia-causative proteins and UBC, GRB2, CTNNB1, HSP90AA1, CBL, PLCG1, and CRK were listed as the most commonly-involved downstream proteins." (PMID 31910207, 2020).
interstitial lung disease (1 paper, 2024). A diverse group of lung diseases that affect the lung parenchyma. "Of note, the expression of driver mutations in EGFR, BRAF, and KRAS G12C in patients with NSCLC with concurrent interstitial lung disease is vastly different compared to those patients with NSCLC without Interstitial Lung Disease." (PMID 39062713, 2024).
intracranial hemorrhage (1 paper, 2018). Bleeding within the SKULL, including hemorrhages in the brain and the three membranes of MENINGES. "One KRAS-variant patient had a sporadic AVM restricted to the intracranial cavity; this patient presented with an intracranial hemorrhage at the age of 13." (PMID 29461977, 2018).
kidney stone (1 paper, 2024). "We conducted enrichment analysis of 50 signature gene sets using the ssGSEA algorithm, revealing significant differences in several signature gene sets between the kidney stone group and the control group, including downregulation of KRAS signaling transduction and markers of spermatogenesis." (PMID 39606015, 2024).
lung fibrosis (1 paper, 2017). "Conversely, the low prevalence of KRAS mutations, contrasting with the high percentage of smokers, also supports a role for endogenous carcinogenic mechanisms linked to lung fibrosis." (PMID 28619094, 2017).
lymphangitis (1 paper, 2016). Inflammation of the lymphatic vessels. "In this study, we found that EGFR mutations were associated with GGO, KRAS mutations were associated with solid tumors that had low tendencies to metastasize to the lung and pleura, and ALK rearrangements were associated with lymph node involvement and lymphangitis." (PMID 27518729, 2016).
malignant germ cell tumor (1 paper, 2020). A gonadal or extragonadal malignant neoplasm that arises from germ cells. "Malignant germ cell tumors have a low mutational burden, but the KIT, KRAS, TGF-BMP, and Wnt-catenin signaling pathway inhibitors and anti-CD30 immunotherapy can be used as targeted therapies in patients with resistant disease." (PMID 33352733, 2020).
mesonephric adenocarcinoma (1 paper, 2019). An adenocarcinoma of the cervix or the vagina arising from mesonephric remnants. "KRAS/NRAS mutations are the most common molecular alterations detected in mesonephric adenocarcinomas." (PMID 31266530, 2019).
monocytic leukemia (1 paper, 2023). "PTPN11mut was more common in myelomonocytic and monocytic leukemia, and was more likely to co‐mutate with KRAS, KMT2C, NRAS, U2AF1, NOTCH1, IKZF1, and USH2A mutations than PTPN11wt." (PMID 37937729, 2023).
Moyamoya disease (1 paper, 2024). Moyamoya disease (MMD) is a rare intracranial arteriopathy involving progressive stenosis of the cerebral vasculature located at the base of the brain causing transient ischemic attacks or strokes. "Therefore, we can infer that in moyamoya disease, STK3 will promote the proliferation of VSMCs through the KRAS signaling pathway, HEDGEHOG signaling pathway and others in a similar way." (PMID 38704490, 2024).
mucinous bronchioloalveolar adenocarcinoma (1 paper, 2021). A bronchiolo-alveolar adenocarcinoma that is characterized by a tumor cells containing abundant mucin in their cytoplasm and composed of tall columnar cells growing along alveolar walls without stromal invasion. "It has been demonstrated that IMA (formerly mucinous bronchioloalveolar adenocarcinoma) correlates with the presence of KRAS mutations." (PMID 34026636, 2021).
nerve sheath tumors (1 paper, 2015). "The other KRAS-derived tumors with spindle cell morphology were compatible with human MPNSTs, which are aggressive nerve sheath tumors associated with activation of the RAS pathway." (PMID 25644510, 2015).
non-alcoholic fatty liver disease (1 paper, 2021). "HDL-bound miR-17-5p, HDL-bound miR-532-5p, HDL-bound miR-143-3p and HDL-bound miR-185-5p were involved in the Ras signalling pathway, and KRAS could alleviate high-fat diet-induced non-alcoholic fatty liver disease by inhibiting the synthesis and promoting beta-oxidation of fatty acids." (PMID 34090327, 2021).
oral cavity cancer (1 paper, 2020). A primary or metastatic malignant neoplasm involving the oral cavity. "Subsite analysis showed that, in oral cavity cancer, KRAS mutations occur in 0.32% in TCGA-HNC but 1.85% in MSK-IMPACT." (PMID 33053752, 2020).
oral epithelial dysplasia (1 paper, 2022). "The paraffin-embedded tissue was analyzed for the expression of KRAS for oral epithelial dysplasia and OSCC, and ki-67, Cyclin D1, and bcl2 were analyzed only for OSCC." (PMID 36532636, 2022). "The KRAS expression in oral epithelial dysplasia was significantly lower than that in OSCC (P=0.003)." (PMID 36532636, 2022). "On the immunohistochemical evaluation of KRAS staining, only one case (5%) of the 20 examined cases of oral epithelial dysplasia showed high expression, while the rest of the cases showed no or weakly positive expression (low expression)." (PMID 36532636, 2022).
Osteopenia (1 paper, 2025). Osteopenia is a term to define bone density that is not normal but also not as low as osteoporosis. "Patients with osteopenia are more likely to develop lung metastases, and BMD-value reduction associated with KRAS mutation." (PMID 40549756, 2025).
ovarian cystadenoma (1 paper, 2022). A benign ovarian surface epithelial-stromal tumor characterized by the presence of cystic structures lined by serous epithelial cells, mucinous columnar epithelial cells, or endometrial-type well-differentiated cells. "Thus, we generated immortalized epithelial cells from ovarian cystadenoma cells and introduced oncogenic KRAS, PIK3CA, and KRAS + PIK3CA mutations, which appeared to be the most essential for developing LGSOCs." (PMID 35326657, 2022).
ovarian mucinous borderline tumor (1 paper, 2024). "We report a case of PMP arising from an ovarian mucinous borderline tumor with a KRAS mutation, which achieved complete remission following bevacizumab-containing chemotherapy." (PMID 39310419, 2024). "We reported a case of PMP arising from an ovarian mucinous borderline tumor with a KRAS mutation, which achieved complete remission with a bevacizumab-containing chemotherapy regimen." (PMID 39310419, 2024). "The final pathological diagnosis was PMP originating from an ovarian mucinous borderline tumor staged as pT1CNxMx, with KRAS G12V mutation." (PMID 39310419, 2024). "The patient was diagnosed with PMP arising from an ovarian mucinous borderline tumor with a KRAS mutation." (PMID 39310419, 2024).
ovarian mucinous cystadenoma (1 paper, 2024). "High-throughput sequencing identified KRAS mutations in the ovarian mucinous cystadenoma." (PMID 39220649, 2024).
pancreatic serous cystadenoma (1 paper, 2024). A benign, non-metastasizing cystic epithelial neoplasm arising from the exocrine pancreas. "There was a single case of cftDNA positivity (mutation in the KRAS G12/13 hotspot) in the OPN group, specifically in the plasma sample from a patient diagnosed with a pancreatic serous cystadenoma (however, the cftDNA level was extremely low—2.34 copies/mL with a MAF of 0.12%)." (PMID 38255325, 2024).
parasitic infection (1 paper, 2020). "In the up-regulated proteins focal adhesion, various cancers, ECM-receptor interaction, EGFR/GRB2/KRAS (annotated here as dorso-ventral axis formation), and Gap and adherens junctions featured, as did pathways related to bacterial and parasitic infection." (PMID 32161586, 2020).
parathyroid carcinoma (1 paper, 2023). "Other mutations in KMT2D, KRAS (in-frame deletion), and FRAT2 (FRAT regulator of WNT signaling pathway 2) are potentially associated with the oncogenesis of parathyroid carcinoma; however, the evidence remains limited." (PMID 37121965, 2023).
periampullary adenocarcinoma (1 paper, 2019). An adenocarcinoma that arises from the periampullary region. "The results from this study demonstrate that stromal PR expression, together with KRAS mutation status, provides long-term prognostic information in particular in female patients with pancreatic and other periampullary cancers." (PMID 31827798, 2019).
pneumothorax (1 paper, 2024). Abnormal presence of air in the pleural cavity. "Notably, in 20 normal lung tissues form pneumothorax patients, the AmoyDx detected KRAS G12C mutation (n = 1) and ROS1 fusion (n = 1)." (PMID 38816489, 2024).
progeria (1 paper, 2022). "For instance, the only hallmark gene set that is enriched when comparing progeria patients and healthy children is KRAS signaling up." (PMID 36289702, 2022). "While normal aging appears to affect the cell cycle G2/M checkpoint (G2M checkpoint), E2F targets, and the mitotic spindle assembly (hallmark MITOTIC_SPINDLE), progeria is only associated with KRAS signaling up, the genes upregulated by KRAS (Kristen rat sarcoma virus) activation." (PMID 36289702, 2022).
pulmonary adenoid cystic carcinoma (1 paper, 2015). "The data presented in this work suggest that EGFR, KRAS, BRAF, ALK, PIK3CA, PDGFRA, and DDR2 may not be driver genes in primary pulmonary adenoid cystic carcinoma." (PMID 26373952, 2015).
reactive disorder (1 paper, 2025). "Recent studies have shown that approximately one-third of patients with RDD harbor mutations in genes involved in the MAPK/ERK pathway, such as NRAS, KRAS, MAP2K1, and, rarely, BRAF, indicating a neoplastic process rather than a reactive disorder." (PMID 40385897, 2025).
rectal mucinous adenocarcinoma (1 paper, 2025). "The second patient was female with rectal mucinous adenocarcinoma and synchronous bone metastases and presented with KRAS c.35G>T (p.Gly12Val) and NRAS c.38G>T (p.Gly13Val) mutations." (PMID 40075837, 2025).
rectosigmoid adenocarcinoma (1 paper, 2019). An adenocarcinoma arising from the rectosigmoid area. "A 56-year-old man was diagnosed with KRAS G12C mutated stage IIIB rectosigmoid adenocarcinoma." (PMID 30923702, 2019).
Richter syndrome (1 paper, 2020). Transformation of chronic lymphocytic leukemia into aggressive non-Hodgkin's lymphoma, usually diffuse large B-cell lymphoma (immunoblastic or centroblastic variant).
schizophrenia (1 paper, 2022). A major psychotic disorder characterized by abnormalities in the perception or expression of reality. "In summary, we report that penfluridol, a drug for treating schizophrenia in the clinic, can suppress mitochondrial OXPHOS through targeting the SIRT1/PGC-1α axis to reduce ATP production, especially in mutant KRAS-expressing NSCLC cells." (PMID 35681729, 2022).
scrapie (1 paper, 2025). A fatal disease of the nervous system in sheep and goats, characterized by pruritus, debility, and locomotor incoordination. "In contrast, gene expression in the thalamus showed greater variability, and significant downregulation was detected only for KRAS and CLTC in clinical scrapie animals compared with healthy controls." (PMID 40597437, 2025).
seborrheic keratosis (1 paper, 2021). A common benign skin neoplasm usually affecting older individuals. "Briefly, we observed a HRAS G12D mutation in 1 out of 5 SCC, KRAS G12D mutation 1 (out of 3) BBC and in the sebaceous hyperplasia case, HRAS Q61L in 1 (out of 3) BCC and a HRAS Q61K mutation was found in 1 out of 5 seborrheic keratosis." (PMID 33747359, 2021).
skin angiosarcoma (1 paper, 2025). A malignant vascular neoplasm arising from the skin. "The KRAS V14I mutation identified in our case has been described in a previously reported case of skin angiosarcoma." (PMID 40012695, 2025).
Spinal neurofibroma (1 paper, 2025). A neurofibroma (benign peripheral nerve sheath tumor) localized in the spine. "We report a child presenting with pigmentary skin lesions and spinal neurofibromas who was diagnosed molecularly with KRAS mosaicism." (PMID 40682439, 2025).
Spitz nevi (1 paper, 2021). "Consecutive to Spitz nevi exclusion, KRAS sensitivity was not changed (71.88%), whereas BRAF specificity was slightly higher (65.22%)." (PMID 34769348, 2021).
systemic mastocytosis (1 paper, 2025). Systemic mastocytosis (SM) comprises a heterogeneous group of rare acquired and chronic hematological malignancies that are related to an abnormal proliferation of mast cells in tissue, including bone marrow, with or without skin involvement. "Other somatic gene alterations implicated in some cases of advanced systemic mastocytosis include mutations in TET2, SRSF2, ASXL1, RUNX1, CBL, JAK2, NRAS, and KRAS." (PMID 41440762, 2025). "Interestingly, NGS analysis did not detect any mutations in all the other KIT exons analyzed nor in other genes previously reported in patients with advanced systemic mastocytosis (TET2, SRSF2, ASXL1, RUNX1, CBL, JAK2, NRAS, and KRAS)." (PMID 41440762, 2025).
T-lymphoblastic lymphoma/leukemia (1 paper, 2021). "While KRAS is mutated in many tumors including non-hematopoietic malignancies, T-lymphoblastic lymphoma/leukemia (T-ALL), which accounts for up to 15% of pediatric and 25% of adult ALL cases, may have a KRAS G12D mutation." (PMID 33801781, 2021).
testicular tumors (1 paper, 2021). "KRAS mutations were present in 10% of testicular tumors, while fewer than 5% of samples contained mutations in NRAS, PIK3CD, and PIK3CA genes." (PMID 34819066, 2021).
tumors of the nasopharynx (1 paper, 2022). "In contrast, KRAS mutations were more frequent in sinonasal tumors, and NRAS mutations were found chiefly in tumors of the nasopharynx." (PMID 35600380, 2022). "In contrast, KRAS mutations are found more frequently in sinonasal tumors, and NRAS mutations are found chiefly in tumors of the nasopharynx." (PMID 35600380, 2022).